POMT2 (protein O-mannosyltransferase 2)
Description:
Transfers mannosyl residues to the hydroxyl group of serine or threonine residues. Coexpression of both POMT1 and POMT2 is necessary for enzyme activity, expression of either POMT1 or POMT2 alone is insufficient. Essentially dedicated to O-mannosylation of alpha-DAG1 and few other proteins but not of cadherins and protocaherins.
Synonyms: LGMD2N; LGMDR14; MDDGA2; MDDGB2; MDDGC2
Tractability: Antibody: UniProt predicts a signal peptide or a membrane-spanning region.
Gene: Protein-coding gene on chromosome 14 (77,274,956 to 77,320,883, reverse strand). Ensembl gene ENSG00000009830.
Subcellular location: Endoplasmic reticulum membrane
Subcellular location (Human Protein Atlas): Nucleoplasm; Cytosol; Nucleoli
Pathways (Reactome):
Metabolism of proteins: DAG1 core M1 glycosylations; DAG1 core M2 glycosylations; DAG1 core M3 glycosylations
Disease: Defective POMT1 causes MDDGA1, MDDGB1 and MDDGC1; Defective POMT2 causes MDDGA2, MDDGB2 and MDDGC2
Cell-Cell communication: Regulation of CDH1 posttranslational processing and trafficking to plasma membrane
Gene Ontology:
Molecular function: mannosyltransferase activity; dolichyl-phosphate-mannose-protein mannosyltransferase activity
Biological process: protein O-linked glycosylation via mannose; protein O-linked glycosylation
Cellular component: dolichyl-phosphate-mannose-protein mannosyltransferase complex; endoplasmic reticulum membrane; endoplasmic reticulum; membrane
Genetic constraint (gnomAD): Loss-of-function variants: 75 observed, 96.29 expected, observed/expected ratio (o/e) 0.78, 90% interval 0.65 to 0.94. The upper end of that interval is the gene's LOEUF score, 0.94, which puts it in group 4 of 6, group 1 being the genes least tolerant of losing a copy. Missense variants: 938 observed, 927.41 expected, observed/expected ratio (o/e) 1.01, 90% interval 0.96 to 1.07. Synonymous variants: 378 observed, 355.83 expected, observed/expected ratio (o/e) 1.06, 90% interval 0.98 to 1.16.
Gene-disease validity (ClinGen):
ClinGen rates the evidence that POMT2 causes each of these diseases.
myopathy caused by variation in POMT2 (autosomal recessive): Definitive. Any myopathy in which the cause of the disease is a variation in the POMT2 gene.
Homologues: Orthologues: chimpanzee POMT2 (99% identical), macaque POMT2 (97% identical), dog POMT2 (91% identical), pig POMT2 (91% identical), mouse Pomt2 (91% identical), rat Pomt2 (90% identical), guinea pig POMT2 (89% identical), rabbit POMT2 (89% identical), zebrafish pomt2 (66% identical), tropical clawed frog pomt2 (65% identical), Drosophila melanogaster tw (52% identical). Paralogues in human: POMT1 (32% identical), SDF2L1 (9% identical), SDF2 (9% identical).
Diseases named in the same sentence as POMT2 in open-access papers:
POMT2 is named in the same sentence as 31 diseases in open-access papers, as found by Europe PMC text mining. Sharing a sentence is not in itself a finding about the gene and the disease. The quoted sentences say what the papers report.
dystroglycanopathies (19 papers, 2013 to 2026). "While the functional consequence of this exon inclusion is unclear, POMT2 is linked to muscular dystrophies, i.e., dystroglycanopathies." (PMID 40343270, 2025). "Very similar brain involvement was found in WWS patients with genetically confirmed dystroglycanopathy due to mutations in other genes like POMT2, LARGE, POMGnT1 and FUKUTIN, respectively." (PMID 31311558, 2019). "We have observed that within our cohort, suspected pathogenic mutations in POMT2 are the most common cause of dystroglycanopathies." (PMID 30060766, 2018). "Because Emx1Cre (and NestinCre) conditional deletion of Dag1 or Pomt2 leads to widespread loss of functional Dystroglycan in the forebrain in contrast with the previously studied NeuroD6Cre conditional deletion, which targets pyramidal neurons, these models more accurately model dystroglycanopathy." (PMID 38179984, 2024). "Ultimately, our study extended the phenotypic and genetic spectrum of POMT2-associated LGMDR14 and provided valuable insights into subsequent accurate diagnosis and potential treatment strategies for alpha-dystroglycanopathies." (PMID 40102912, 2025). "Mice that model severe dystroglycanopathy due to forebrain deletion of Dag1 or Pomt2, which is required for Dystroglycan glycosylation, show significant impairment of CCK+/CB1R+ IN development." (PMID 38179984, 2024). "LGMD R7 telethonin-related was found in 14.6% (6/41) of index patients, and dystroglycanopathies (including mutations in FKRP, POMT1, POMT2 and ISPD) were found in 12.2% (5/41) of index patients." (PMID 37974208, 2023). "Due to the enrichment of regulatory variants in FKTN and DTNA, we expanded our search to additional dystroglycanopathy genes (LARGE1, POMT1, POMT2) and identified two regulatory variants of interest in LARGE1 in gene-elusive cases." (PMID 35288587, 2022). "Specifically, a form of dystroglycanopathy, a limb-girdle muscular dystrophy (type C2; MDDGC2), is caused by homozygous or compound heterozygous mutation in the POMT2 gene." (PMID 31959160, 2020). "Similar results have previously been reported in dystroglycanopathy patients with Protein-O-mannosyl transferase 1 (POMT1), Protein-O-mannosyl transferase 2 (POMT2), POMGnT1, FKTN and FKRP mutations." (PMID 30553274, 2018). "Emx1Cre:Dag1 cKO and Emx1Cre:Pomt2 cKO mice show Type II lissencephaly consistent with severe dystroglycanopathy, whereas B4gat1M155T/M155T and FkrpP448L/P448L mutants have relatively normal cortical development consistent with mild dystroglycanopathy." (PMID 38179984, 2024). "(d) Several subtypes of LGMDs are dystroglycanopathies, primarily caused by mutations in eight genes, including FKRP (R9), POMT1 (R11), FKTN (R13), POMT2 (R14), POMGnT1 (R15), GMPPB (R19), ISPD (R20), and POMGNT2 (R24), involved in the glycosylation of the alpha-dystroglycan pathway." (PMID 37974208, 2023). "Furthermore, POMT2, encoding O-mannoyltransferase 2 (POMT2), is one of the pathogenic genes of α-DGP (Alpha-dystroglycanopathy)." (PMID 36496988, 2022). "Other genes contributing to dystroglycanopathies through glycosylation errors include POMT1, POMT2, POMGNT1, FKRP, ISPD and LARGE1." (PMID 38439105, 2024). "It must be noted that rather than mutations in POMT2, those in FKRP are widely considered to cause the commonest dystroglycanopathy in Europe, LGMD2I." (PMID 30060766, 2018). "Among dystroglycanopathies, good correlation between α-DG staining and disease course was demonstrated in only a few forms (POMT1, POMT2, and POMGnT1-mutated cases), and is absent in patients with mutations in FKRP and FKTN." (PMID 26404900, 2015).
Walker-Warburg syndrome (14 papers, 2015 to 2025). "In fact, Patient #46 presented with a pathogenic variant in POMT2 and had stigmata of Walker--Warburg syndrome, including bilateral congenital cataracts, epileptic encephalopathy, and muscle weakness." (PMID 36980880, 2023). "Mutations in POMT2 often cause Walker-Warburg syndrome, whereby afflicted patients die during early childhood." (PMID 36499139, 2022). "POMT2 deficiency was initially associated with Walker-Warburg syndrome, a congenital disease with brain, eye and muscle affections, while mutations in the gene were only later described to be associated with LGMD2N." (PMID 30060766, 2018). "Currently, POMT2-related disorders include Walker-Warburg syndrome (WWS), congenital muscular dystrophy (CMD) and limb girdle muscular dystrophy type R14 (LGMDR14)." (PMID 40102912, 2025). "The most severe phenotype of POMT2-related α-DGP is Walker-Warburg syndrome [WWS, (OMIM 236670)], with an onset of intrauterine or after birth." (PMID 34413876, 2021). "Clinically, POMT2 deficiency is often associated with a wide range of clinical involvement, ranging from severe muscle–eye–brain disease and Walker–Warburg syndrome to limb–girdle muscular dystrophy without structural brain or ocular involvement." (PMID 37239976, 2023). "For instance, in D. melanogaster, POMT1 and POMT2 are required for maintaining the integrity of larval muscles and normal axonal connections of sensory neurons, while in humans, mutations in POMT1 and POMT2 lead to Walker–Warburg syndrome." (PMID 33922798, 2021).
muscular dystrophies (10 papers, 2018 to 2025). "Surprisingly, it is revealed that homozygous variants of POMT2 is related to muscular dystrophy, displaying hypotonia, low left ventricular ejection and mild restrictive lung disease." (PMID 37860673, 2023). "Genetic defects in either protein O-mannosyltransferase, POMT1 or POMT2, underlie severe muscular dystrophies in humans." (PMID 31959160, 2020). "In addition to retinal atrophy, POMT2 mutation in human patients causes type II lissencephaly, hydrocephalus, and hypoplasia of the cerebellum, as well as muscular dystrophy." (PMID 36499139, 2022). "In the LOH region, we found a homozygosity of POMT2 variants could result in muscular dystrophy." (PMID 37860673, 2023). "In the group of congenital muscular dystrophies, 11 patients received a genetic diagnosis with mutations in the following genes: LAMA2 (three cases); POMGNT1 (one case); COL6 (one case); TTN (one case); GMPPB (one case); POMT2 (one case); POMGNT2 (one case); DMD (one case); and SCGA (one case)." (PMID 34675869, 2021). "Although it is possible that the lower limb hypotonia and the intellectual disability found in this patient are caused by the biallelic variant allele in POMT2, this subject does not have features of muscular dystrophy; therefore, we consider this an unlikely possibility." (PMID 31014393, 2019). "However, although the subject presents with hypotonia, he does not have features of muscular dystrophy and does not have severe intellectual disability as can be observed in individuals with POMT2 pathogenic alleles." (PMID 31014393, 2019).
congenital muscular dystrophy (4 papers, 2018 to 2025). A muscular dystrophy that is characterized by diminished muscle tone (hypotonia), progressive muscle weakness and degeneration (atrophy), abnormally fixed joints, spinal rigidity, and delays in reaching motor milestones such as sitting or standing unassisted. "Mutations in POMT2 cause severe congenital muscular dystrophy and are associated with a milder limb-girdle muscular dystrophy phenotype." (PMID 29949603, 2018).
gastric cancer (3 papers, 2016 to 2023). A primary or metastatic malignant neoplasm involving the stomach. "A previous study on POMT2 target proteins in gastric cancer has shown the existence of a coordinated interplay between O-mannosylation and N-glycosylation pathway." (PMID 37221403, 2023). "In recent years, it turned out that changes in classic O-mannosylation due to altered expression of POMT2 impact also on epithelial cadherin (E-Cdh)-mediated cell–cell adhesion during murine embryonic development and in human gastric carcinoma." (PMID 33610554, 2021). "Altered POMT2 expression in gastric cancer cells consistently resulted in altered expression of branched complex N-glycans on E-cadherin in an inverse and coordinated manner." (PMID 27533452, 2016).
breast carcinoma (2 papers, 2019 to 2022). "A weak negative correlation was observed between EZH2 and its targets in breast cancer cell lines MERAV dataset (except for POMT2 and VGLL4 where a positive correlation was detected)." (PMID 30760814, 2019). "A concomitant improved relapse free survival in breast cancer patients with increased expression of POMT2, PMEPA1 and SUMF1 indicated their tumor suppressive behavior." (PMID 30760814, 2019). "ER independent expression of POMT2 was observed in breast cancer cells." (PMID 30760814, 2019). "In MDA-MB-231 breast cancer cells, reduced mRNA expression of EZH2 was detected upon DZNepA treatment whereas increased expression of its target genes (except POMT2 and VGLL4) was found." (PMID 30760814, 2019). "Upon EZH2 knockdown, fold change in the target gene expression for GPNMB, CoL5A1, POMT2, PMEPA1, VGLL4 and SUMF1 was found to be 1.3, 2.8, 2.2, 2, 1.7 and 1.8, respectively in MCF-7 breast carcinoma cells as detected by qPCR." (PMID 30760814, 2019). "KM plotter analysis showed improved relapse-free survival with increased expression of PMEPA1, POMT2, VGLL4 and SUMF1 in breast cancer patients indicating their therapeutic potential." (PMID 30760814, 2019). "The POMT2 gene (but not POMT1) has been found underexpressed in the breast cancer cell lines MCF7, MDA-MB-231, MDA-MB-253 and T47D, in keeping with observations in samples from patients with breast cancer." (PMID 36494657, 2022). "Interestingly, POMT2 positively correlated with EZH2 in breast cancer cells along with non-cancerous cell lines whereas in primary breast tumor and normal breast tissues, a negative correlation existed between the two." (PMID 30760814, 2019).
Intellectual disability (2 papers, 2016 to 2019). "Pathogenic variants in POMT2 can cause one of three types of recessive muscular dystrophy-dystroglycanopathy: congenital with brain and eye anomalies, type A, 2 (MDDGA2, MIM#613150); congenital with mental retardation, type B, 2 (MDDGB2, MIM#613156); and limb-girdle, type C, 2 (MDDGC2, MIM#613158)." (PMID 31014393, 2019).
idiopathic inflammatory myositis (1 paper, 2022). "Other target conditions could include idiopathic inflammatory myositis and myopathies due to mutations in fukutin and POMT2." (PMID 35625891, 2022).
myopia (1 paper, 2018). "The phenotypic subset associated with myopia (n = 130) was found to represent a set of 119 unique genes since 7 genes (COL2A1, COL11A1, FBN1, LTBP2, POMT1, POMT2, POMGNT1) had two or more associated phenotypes, leading to 11 duplicates." (PMID 29346494, 2018).
brain disease (2 papers, 2023). "POMT2 and POMGNT1 are involved in two clinically similar disorders, respectively Walker–Warburg syndrome (WWS) and muscle–eye–brain disease (MEB)." (PMID 36859317, 2023).
cancer (2 papers, 2016 to 2019). A tumor composed of atypical neoplastic, often pleomorphic cells that invade other tissues. "In the present study, we validated six direct targets of EZH2 that are GPNMB, PMEPA1, CoL5A1, VGLL4, POMT2 and SUMF1 associated with cancer related pathways." (PMID 30760814, 2019). "In a cancer cell, both the POMT2 gene and enzyme are downregulated and consequently the pattern of E-cadherin O-mannosylation decreases." (PMID 27533452, 2016).
tumor (2 papers, 2019 to 2022). "Additionally, the POMT2 mRNA was underexpressed in breast tumor samples, which correlated with a reduced relapse-free survival and increased tumor aggressiveness." (PMID 36494657, 2022). "GPNMB and CoL5A1 are the reported oncogenes; PMEPA1, POMT2, VGLL4 and SUMF1 show better survival and thus suggest tumor suppressive role are being regulated by EZH2 signifying its dual role." (PMID 30760814, 2019).
POMT2 also shares sentences with these, for which no sentence is quoted: limb-girdle muscular dystrophy (3 papers); Lissencephaly (2); Secondary dystroglycanopathies (2); breast tumor (1); capillary malformation (1); Cerebellar hypoplasia (1); cobblestone lissencephaly (1); congenital cataracts (1); congenital hydrocephalus (1); congenital myopathies (1); epilepsy (1); Epileptic encephalopathy (1); gastroschisis (1); Hydrocephalus (1); muscle-eye-brain disease (1); myopathies (1); polymicrogyria (1); restrictive lung disease (1); Retinal atrophy (1).